MEI4 (meiotic double-stranded break formation protein 4)
Description:
Required for DNA double-strand breaks (DSBs) formation in unsynapsed regions during meiotic recombination. Probably acts by forming a complex with IHO1 and REC114, which activates DSBs formation in unsynapsed regions, an essential step to ensure completion of synapsis.
Tractability: No criterion of Open Targets' tractability assessment is met for any kind of drug.
Gene: Protein-coding gene on chromosome 6 (77,650,274 to 77,927,045, forward strand). Ensembl gene ENSG00000269964.
Subcellular location: Chromosome
Gene Ontology:
Molecular function: protein binding
Biological process: homologous chromosome pairing at meiosis; meiotic DNA double-strand break formation; oogenesis; spermatogenesis; DNA recombination
Cellular component: chromosome; condensed nuclear chromosome; lateral element
Genetic constraint (gnomAD): Loss-of-function variants: 29 observed, 29.49 expected, observed/expected ratio (o/e) 0.98, 90% interval 0.73 to 1.34. The upper end of that interval is the gene's LOEUF score, 1.34, which puts it in group 5 of 6, group 1 being the genes least tolerant of losing a copy. Missense variants: 319 observed, 412.53 expected, observed/expected ratio (o/e) 0.77, 90% interval 0.7 to 0.85. Synonymous variants: 122 observed, 150.83 expected, observed/expected ratio (o/e) 0.81, 90% interval 0.7 to 0.94.
Homologues: Orthologues: chimpanzee MEI4 (99% identical), macaque MEI4 (95% identical), rabbit MEI4 (78% identical), pig MEI4 (77% identical), dog MEI4 (76% identical), mouse Mei4 (72% identical), rat Mei4 (70% identical), guinea pig MEI4 (56% identical), tropical clawed frog mei4 (38% identical), zebrafish mei4 (26% identical).
Diseases named in the same sentence as MEI4 in open-access papers:
MEI4 is named in the same sentence as 1 disease in open-access papers, as found by Europe PMC text mining. Sharing a sentence is not in itself a finding about the gene and the disease. The quoted sentences say what the papers report.
tumor (1 paper, 2025). "Five genes - CHRNA4, AC084026.2, AC015910.1, MEI4, and AC025062.3 - exhibited decreased expression levels in tumor samples compared to normal tissue." (PMID 40356901, 2025). "The downregulation of CHRNA4, AC084026.2, AC015910.1, MEI4, and AC025062.3 in tumor samples suggests that these genes may act as tumor suppressors, while the upregulation of the other identified hub genes implies a possible oncogenic role." (PMID 40356901, 2025).